ANKRD18CP (ankyrin repeat domain 18C, pseudogene)
Gene: Transcribed unprocessed pseudogene on chromosome 9 (97,156,570 to 97,221,235, reverse strand). Ensembl gene ENSG00000159712.
Diseases named in the same sentence as ANKRD18CP in open-access papers:
ANKRD18CP is named in the same sentence as 1 disease in open-access papers, as found by Europe PMC text mining. Sharing a sentence is not in itself a finding about the gene and the disease.
ANKRD18CP shares sentences with these, for which no sentence is quoted: cervical cancer (1 paper).